CCL2 (C-C motif chemokine ligand 2)
Diseases named in the same sentence as CCL2 in open-access papers (continued):
Sharing a sentence is not in itself a finding about the gene and the disease.
kidney damage (80 papers, 2009 to 2025). "Indiabetic nephropathy, urinary CCL2 was directly related to the risk of CKDprogression in patients with macroalbuminuria." (PMID 34251390, 2022). "We demonstrated that Lin28A OE in non-hematopoietic lineage can trigger an inflammatory response via the rapid upregulation of several cytokines, including CXCL1 and CCL2, leading to severe kidney damage." (PMID 39113694, 2024). "RAGE229 treatment reduced plasma concentrations of TNF-α, IL-6 and CCL2/JE-MCP1 in diabetic mice, while reducing pathological and functional indicators of diabetic-like nephropathy." (PMID 35967420, 2022). "In patients with CKD, interstitial macrophage numbers in kidney biopsies are closely correlated with kidney damage, with urinary CCL2 levels and interstitial macrophage numbers interdependent parameters in multivariate analysis." (PMID 35203629, 2022). "C-C motif chemokine 2 (CCL2) secreted from mesangial cells, participates in renal infiltration and kidney damage during the progression of DKD." (PMID 32992874, 2020). "Injecting mice with CCL2 causes tubulointerstitial inflammation, an enhanced inflammatory response, and macrophage migration, whereas increased levels of CCL2 in humans induce proteinuria in nephropathy patients." (PMID 30987213, 2019). "Compared with control mice, WT mice with LPS nephropathy had higher CCL2 gene expression in the kidney." (PMID 29862277, 2018). "Conversely, the blockade of CCL2/CCR2 interaction by either neutralization of CCL2 or CCR2 antagonists has been shown to attenuate progressive kidney damage." (PMID 25807547, 2015). "The co-occurrence of risk associated genotypes (II, -2518GG (CCL2), DD (CCR5) and 279Gln/Gln (MMP9) conferred a tenfold increased risk of nephropathy among type 2 diabetics (p<0.0002)." (PMID 19357773, 2009). "Also referred to as CCL2, it is a key mediator of innate immunity involved in kidney disease-related inflammation and its expression directly correlates with the severity of nephropathy." (PMID 39201667, 2024). "Vagus nerve stimulation has been shown to reduce the expression of cytokines and chemokines, including CCL2, a potent chemokine which attracts monocytes/macrophages, and this is accompanied by a decrease in the number of infiltrating macrophages in cisplatin-induced nephropathy." (PMID 38794117, 2024). "In the adriamycin-induced mouse model of nephropathy, researchers found that CCL2 in the kidney may recruit the infiltration of inflammatory and pro-fibrotic bone marrow-derived cell populations through its receptor CCR2; furthermore, a deficiency of Ccr2 in mice can ameliorate renal injury." (PMID 37908345, 2023). "LPS-triggered AKI additionally elevated pro-inflammatory cytokines, such as IL-6, Ccl2, and TNFα, while Inhibiting antioxidant enzymes like GSH, SOD, and GPX, resulting in oxidative stress and kidney damage." (PMID 40225865, 2025). "Among 23 cytokines tested, the levels of four cytokines—CCL2, CCL11 (Eotaxin), G-CSF, and IL-12(p40)—were significantly reduced by VNS in cisplatin-induced nephropathy mice." (PMID 32528023, 2020). "In fact, a series of studies showed that these two respective chemokine targets mediate different pathomechanisms of kidney diseases and dual blockade of CCL2 and CXCL12 leads to additive effects on the in prevention of progression of nephropathy and proliferative lupus nephritis." (PMID 39492831, 2024).
coronary artery disease (79 papers, 2007 to 2025). "Genome-wide association studies (GWASs) have linked genetic variation at the CCL2 locus to coronary artery disease and other inflammation-related phenotypes and diseases." (PMID 33495464, 2021). "Furthermore, high circulating levels of IL-8 and CCL2 have been found in obese subjects increasing the risk of coronary artery disease and type 1 or 2 diabetes." (PMID 24040759, 2013). "In another study, MCP1 (HGNC alias: CCL2) was found significantly upregulated in CD14+ monocytes of patients with coronary heart disease." (PMID 37504561, 2023). "Plasma levels of CCL2 were found to be significantly increased in patients with coronary heart disease compared to healthy individuals." (PMID 33540898, 2021). "CCR2 has a crucial function in scavenger of CCL2 from the blood and a dysfunction in CCR2 is associated with early ischemic heart disease." (PMID 33918875, 2021). "CCL2 has been shown to beinvolved in the pathophysiology of ischemic heart disease; however, the specificeffect of CCL2 on I/R injury remains controversial." (PMID 32696819, 2020). "We found mature HDL particles were reduced in patients with coronary artery disease (CAD), which was associated with an increase in CC-chemokine ligand 2 (CCL2)." (PMID 27458015, 2016). "Likewise, miR-495-3p, which is downregulated in patients with coronary artery disease, targets chemokine (C-C motif) ligand 2 (CCL2) and reduces apoptosis by affecting the cleaved caspase-3 production in HUVECs, as demonstrated in vitro." (PMID 40076710, 2025). "Moreover, the quantitative measurement of CCL2 expression discriminated healthy artery tissue samples from that of coronary artery disease samples in a mild, moderate, or severe state with >85% sensitivity and specificity." (PMID 34356595, 2021). "A study by our research group showed that CCL2 (observed with immunohistochemical staining), was 9-fold higher in coronary arteries obtained by autopsy from patients with coronary artery disease, compared to those of healthy individuals who died in a traffic accident." (PMID 34356595, 2021). "Therefore, the persistent cellular infiltration of the adventitia of aneurysms was associated with an increased M-CSF and PPARγ expression, while the aorta of patients with coronary artery disease showed higher level of chemokine CCL2 and cytokine IL-6." (PMID 26539497, 2015). "Among the results, it was seen that the plasma levels of CCL2 and CX3CL1 were elevated in patients with ACS compared with patients with stable coronary artery disease, and the TC levels in ACS patients of the chemokines CCL2, CCL5, and CX3CL1 were reduced by treatment with colchicine." (PMID 40859641, 2025). "The observed increases in sIL-2R and CCL2 were based on a small sample set in DIALONG, however, the patient characterisation for CVD was performed thoroughly using computed tomography coronary angiography, which enabled the identification of asymptomatic coronary artery disease." (PMID 33193091, 2020). "The monocyte chemoattractant protein-1 (MCP-1/CCL2) is a member of the C-C chemokine family, a potent chemotactic factor for monocytes with potent proinflammatory action attributing to many inflammation mediated diseases, such as T2D and coronary artery disease (CAD)." (PMID 30557342, 2018).
ischemia (79 papers, 2010 to 2026). A hypoperfusion of the BLOOD through an organ or tissue caused by a PATHOLOGIC CONSTRICTION or obstruction of its BLOOD VESSELS, or an absence of BLOOD CIRCULATION. "Another finding about CCL2 and muscle regeneration is a murine model C57Bl/6J where the CCL2 gene was silenced; in this study, after muscle injury caused by ischemia, impaired muscle regeneration was reported." (PMID 39456842, 2024). "The harmful effect of CCL2 has been related to its overexpression in astrocytes, which causes delayed death of the pyramidal neurons after ischemia." (PMID 26355725, 2015). "We identify a novel mechanism where in mLVs recruit macrophages via CCL2 for perivascular clearance post-ischemia." (PMID 41899411, 2026). "Previous studies of UCCAO mouse models have indicated the upregulation of inflammatory chemokines (Ccl2 and Ccl12) as well as ischemia-related genes (Bnip3, Hsp25, and Vegfa) in the retina, and we found similar results with the STZ UCCAO mice." (PMID 40362622, 2025). "Multiple microglia-related genes such as Cxcl10, Tlr7, Cd86, Tnfrsf1a, Nfkbia, Tgfb1, Ccl2 and Il-6, were upregulated with prolonged ischemia." (PMID 35154109, 2022). "CCL2 has previously been identified as a marker for secondary brain ischemia in mice, and it is suggested to be a good therapeutic target in ischemia." (PMID 33918875, 2021). "Upregulation of CCL2 has been confirmed in animal models of traumatic brain injury, cerebral infarction, and ischemia." (PMID 34511129, 2021). "In contrast, ischemia resulted in significantly reduced expression of Ccl2 revealing the opposite impact of MIF protein stimulation." (PMID 30678084, 2019). "While the expression of Mif and proAdm was further increased, the expression of Ccl2 was attenuated from 9.6-fold increased expression after MIF stimulation to 5.6-fold increased expression after ischemia in the presence of MIF." (PMID 30678084, 2019). "Fibrosis in CCL2 KO mice is attenuated at D5 and D7 in an ischemic cardiomyopathy model developed by intermittent daily induction of ischemia/reperfusion." (PMID 27525724, 2016). "Ccl2 was also elevated in Atf3 mutants during cerebral ischaemia indicating a more general mechanism of Ccl2 inhibition by ATF3." (PMID 27581653, 2016). "The main outcome of this work is that the subacute administration of zinc increases the expression of CCL2, CCR2, and growth factors (FGF2 and IGF-1) as well as preventing the loss of memory in the rats after transient hypoxia-ischemia." (PMID 26355725, 2015). "Preliminary investigations demonstrated that the mRNA expression levels of CCL2 in the brain cortex increased significantly at 2 h after ischemia in an ischemia/reperfusion model." (PMID 25009636, 2014). "It was shown in another MCAo study that CCL2 leads to infiltration of the CNS by monocytes and thus enhances brain damage induced by ischemia." (PMID 24324296, 2013). "Although endogenous ligands to TLR4 contribute to lung ischemia-reperfusion injury, the protective effect in Tlr4-/- mice on MCP-1/CCL2 expression and vascular barrier dysfunction were relatively small compared to that seen in Myd88-/- mice." (PMID 24146959, 2013). "Left lung ischemia-reperfusion accounted for 33.9% of the total variance in right lung MCP-1/CCL2 levels (p < 0.001)." (PMID 24146959, 2013). "Brain death may induce CCL2 release in response to ischemia due to peripheral vasoconstriction secondary to catecholamines burst." (PMID 36902067, 2023). "Taken together, a murine model of retinal ischemia by UCCAO could also be used for studying the fundamental role of CCL2 in the development and progression of ischemia-mediated retinal inflammation." (PMID 35005021, 2021). "Then, the upregulated Ccl2/Ccr2 by the combined zinc and selenium administration in the late phase of hypoxia-ischemia might be neuroprotective because they are known to decrease cell death and improve memory." (PMID 30258527, 2018).
ischemia (continued). "This work is focused on CCL2 because it is one of the main chemokines that plays a major role in promoting leukocyte infiltration into the brain parenchyma during ischemia-induced inflammatory response and neuroregeneration including angiogenesis, neurogenesis, and synaptic plasticity." (PMID 26355725, 2015). "In the present study, propofol was shown to significantly downregulate the expression levels of CCL2 and CCR2 in the hippocampal tissues, indicating that propofol may decrease the inflammatory reactions caused by ischemia during reperfusion." (PMID 25009636, 2014). "Similarly, expression of CCL2 was induced in human brain-derived EC by endothelin-1 and ischemia." (PMID 20047691, 2010). "Monocyte Chemotactic Protein-1 (MCP-1)/CCL2 is a chemokine involved in early inflammation and muscle regeneration following hindlimb ischemia in mice." (PMID 29038476, 2017). "In the present study, the effects of preadministration of propofol on the expression levels of CCL2 and CCR2 in the hippocampus were investigated in rats with procerebral ischemia/reperfusion injury." (PMID 25009636, 2014). "Here, we used a model of transient focal cerebral ischemia to explore functional, cellular and molecular responses to ischemia in mice lacking genes for QC, isoQC and their substrate CCL2." (PMID 39272984, 2024). "ATF3/CCL2 was mainly expressed on activated microglia; thus, ATF3/CCL2 may be involved in microglia activation in the brain after ischemia." (PMID 35263513, 2022). "Current evidence points out that the increased level of CCL2, CCL5, and CXCL1 during ischemia plays a dual role and could be either harmful or beneficial." (PMID 26355725, 2015). "An interesting additional finding from our study is that there is significantly increased MCP1/CCL2 expression and MPO activity in the right lung following left lung ischemia-reperfusion and that this right lung response is attenuated in Myd88-/- and, to a lesser extent Tlr4-/- mice." (PMID 24146959, 2013). "Plasma levels of CCL2 did not further increase by 72 h post ischemia onset." (PMID 39272984, 2024). "CCL-2 infusion of the femoral artery of rabbits following hindlimb ischemia increased monocyte accumulation in the vessel wall; a finding that was inhibited with ICAM-1 monoclonal antibody treatment, suggesting that monocyte adhesion to the endothelium in ischemia involves CCL-2 and ICAM-1." (PMID 36465438, 2022).
heart failure (75 papers, 2011 to 2025). Inability of the heart to pump blood at an adequate rate to meet tissue metabolic requirements. "CCL2 is associated with the severity of heart failure, and was found to be expressed in high levels in early burn injury., The timing of this expression coincides with the increased presence of myocytes." (PMID 35743792, 2022). "Lgals3 and Ccl2 have both been implicated in a variety of processes associated with heart failure, including myofibroblast proliferation, fibrogenesis, tissue repair, inflammation, and ventricular remodeling, and both were therefore investigated in our model." (PMID 31354700, 2019). "In parallel, invalidation of CCL2 by gene therapy in a murine model of left-ventricular remodeling and failure improves survival rates and inhibits the cardiac failure characteristics associated with interstitial fibrosis and macrophage infiltration." (PMID 27525724, 2016). "Additionally, hypoxia, which can be both a cause and a result of heart failure, induces CCL2 expression in both right ventricle (RV) and left ventricle (LV) of mice, potentially contributing to cardiac inflammation, fibrosis, and ventricular dysfunction." (PMID 39850880, 2024). "At the same time, elevated levels of cTnT, cTnI, CK, CK-MB, LDH, α-HBDH, CCL2, and CXCL10—hallmarks of cardiovascular pathology—suggested inflammatory responses associated with heart failure." (PMID 40762502, 2025). "Given that both heart failure and IBD have immune-related pathogenesis, a study identified 34 genes associated with immune diseases, including CCL2, through Gene Ontology (GO) and Kyoto Encyclopedia of Genes and Genomes (KEGG) analysis." (PMID 39850880, 2024). "Previous studies discussed the importance of the chemokines above in acute inflammatory response and that Ccl2 may be an effective target for the treatment of heart failure." (PMID 36614295, 2023). "The expression level of CCL2 seems to predict the severity of heart failure." (PMID 37008310, 2023). "Overall, the data indicate that treatment with SCoV2-epitope leads to an increase in the secretion of proinflammatory cytokine GM-CSF while decreasing the secretion of TNF-α, IL-6, and CCL2, which can contribute to the damage of primary cardiomyocytes and potentially lead to cardiac failure." (PMID 38068877, 2023). "Since the CCL2 protein is an important mediator of inflammatory pathways in CFs, which ultimately contribute to heart failure, decreasing CCL2 levels may inhibit pathological inflammatory cascade in the post-ischemic heart." (PMID 37700183, 2023). "In this study, PCI34051 mitigated the heart failure-induced upregulation of Ccl2." (PMID 35126818, 2022). "CCL2, an inflammatory cytokine, plays an important role in the pathogenesis of heart failure." (PMID 35126818, 2022). "Concentrations of MCP-1/CCL-2, EOTAXIN/CCL11 and RANTES/CCL5 were significantly higher in the saliva of heart failure subjects with both NS and HS compared to the controls, while IL-8/CXCL8 level was considerably higher only in heart failure patients with NS." (PMID 36300113, 2022). "Notably, CCL2 and CXCL10 are established biomarkers of heart failure and left ventricular dysfunction (48, –, 52), aligning with the observed ZIKV-induced cardiac pathology." (PMID 40762502, 2025). "Selective activation of the S1P receptor in macrophages suppressed the inflammatory markers tumor necrosis factor-alpha and monocyte chemoattractant protein-1 (CCL2), expedited the reparative marker arginase-1, and was indicative of cardiac repair in the acute phase of heart failure." (PMID 35583622, 2022). "Moreover, targeting inflammatory cytokines and chemokines, such as IL-1, IL-6, CCL2, TGF-β, TNF-α, could be helpful in heart failure treatment." (PMID 34387811, 2022). "Interestingly, Cytl1, also appears to be involved in the pathogenesis of cardiac fibrosis and heart failure (HF), and may be structurally and functionally related to MCP-1 (or CCL2)." (PMID 31089746, 2019).
lupus nephritis (73 papers, 2006 to 2025). Glomerulonephritis in the context of systemic lupus erythematosus. "CCL2, a chemokine that has been implicated as a biomarker for lupus nephritis, was significantly increased in the OAZ silenced group compared to those in the negative control group (298.3 ± 65.3 vs 531.5 ± 46.5, P < 0.05)." (PMID 20359360, 2010). "The role of CCL2 was described in numerous kidney diseases, such as IgA nephropathy, membranous nephropathy, glomerulosclerosis, autosomal dominant polycystic kidney disease, lupus nephritis, GBM‐induced nephritis, ANCA‐associated renal vasculitis, and diabetic nephropathy." (PMID 37382267, 2023). "Recent studies indicate that CCL2 plays a critical role in the chemotaxis of macrophages and neutrophils in lupus nephritis kidneys." (PMID 41208960, 2025). "Meanwhile, in vivo experimental studies have illustrated that blocking CCL2 was effective in inhibiting the progression of proliferative lupus nephritis." (PMID 35702353, 2022). "CCL2 has been observed in the recruitment of T cells and monocytes/macrophages in lupus nephritis and blockade of CCL2 ameliorates lupus nephritis in MRL-(Fas)lpr mice." (PMID 24451065, 2014). "In addition, CCL2 antagonists have been shown to be beneficial in the treatment of lupus nephritis." (PMID 26310926, 2015). "CCL2 (also known as monocyte chemotactic protein-1, MCP-1) and CXCL10 are good biomarkers to indicate the activity of lupus nephritis and the potential flares in SLE." (PMID 26310926, 2015). "In regard to glomerular diseases, high urinary levels of CCL2/MCP-1 have been frequently related to FSGS, lupus nephritis, and IgA nephropathy." (PMID 24692841, 2014). "Similarly to CCL2, chemokine CXCL10 (C‐X‐C motif chemokine ligand 10) has a role in the pathogenesis of kidney diseases such as lupus nephritis or kidney allograft dysfunction." (PMID 37382267, 2023). "In pediatric lupus nephritis, it was recently shown that increased urinary, but not plasma, CCL2/MCP-1 levels correlated with disease activity." (PMID 24692841, 2014). "Additionally, in nephritic lesions of MRLlpr/lpr mice, TLR7 is expressed on renal macrophages and contributes to the production of pro‐inflammatory mediators, including IL‐12, IL‐6, CCL2, and IFN‐α, which is known to contribute to the progression of lupus nephritis." (PMID 28665028, 2017).